EGFR (epidermal growth factor receptor)
Diseases named in the same sentence as EGFR in open-access papers (continued):
Sharing a sentence is not in itself a finding about the gene and the disease.
tumor (continued). "Given that EV biogenesis and secretion are influenced by EGFR signaling, studying their relationship may provide new insights into tumor biology and immune modulation." (PMID 40210802, 2025). "The use of EGFR inhibitors in combination with immunotherapies or anti-inflammatory agents could prove effective in curbing SPINK 6-induced tumor progression." (PMID 40872585, 2025). "However, high expression of PD-L1 in EGFR mutant NSCLC, in theory, should make the tumor susceptible to ICI, shaping the possibility to reactivate the immune system against tumor cells." (PMID 40809430, 2025). "Patients with high TLS density exhibited significantly longer DFS, irrespective of the PD-L1 tumor proportion score or EGFR mutation subtype." (PMID 40723259, 2025). "In summary, EGFR.Sig was observed to be negatively correlated with the tumor immune response." (PMID 40574864, 2025). "Currently, it remains unclear whether blockade of EGFR with cetuximab could influence the selection of different response profiles by reducing tumor mass, releasing neoantigens, or altering HLA expression." (PMID 40869384, 2025). "EGFR protein expression in FDCS might be a consequence of ligand-dependent activation by cognate ligands produced by the tumor microenvironment, which might influence the proliferation of FDCS cells but does not represent per se a proper oncogenic mechanism." (PMID 40646240, 2025). "Additionally, EGFR activation has been implicated in reducing lenvatinib efficacy, as supported by a small clinical trial where the combination of an EGFR inhibitor with lenvatinib elicited a dramatic anti-tumour response and reversed TKI resistance." (PMID 40715090, 2025). "In breast cancer, EXOs displaying targeting ligands such as the GE11 peptide or A15 have been used to deliver chemotherapeutic agents and miRNAs to EGFR- or integrin α_vβ_3-expressing tumor cells, resulting in reduced tumor growth and limited off-target effects in vivo." (PMID 41465256, 2025). "TMED2 has been shown to facilitate EGFR recycling, promoting receptor stability and tumor growth." (PMID 40497947, 2025). "There is mounting evidence supporting EGFR ligands, which are overexpressed in CRC, with potential key roles in tumour progression, as predictive biomarkers for EGFR-targeted therapy sensitivity, as well as mediators of therapy resistance, reviewed in more detail by Guernsey–Biddle and colleagues." (PMID 40940907, 2025). "Specifically, the role of key nephron progenitor transcription factors, such as SIX2, in modulating EGFR expression, and whether intervening in this regulatory pathway could inhibit tumor progression and recurrence, warrants deeper exploration." (PMID 40098972, 2025). "Because of the limited number of patients, the biomarker analysis did not reveal any trends in the presence of specific EGFR mutations or PD‐L1 expression with changes in tumor volume." (PMID 41388935, 2025). "While response rates are generally similar between sexes, women may derive greater benefit from targeted therapies, such as anti-EGFR agents, likely due to differences in tumor biology." (PMID 40805233, 2025). "Drugs such as nimotuzumab could selectively inhibit the proliferation of tumor cells by targeting EGFR, thereby improving prognosis." (PMID 40539040, 2025). "Notably, upfront combination therapy with RET and EGFR inhibitors prevents compensatory EGFR activation, which otherwise contributes to tumor regrowth and resistance to RET inhibitors." (PMID 40405293, 2025). "The surviving EGFR-low cells attract fibroblasts, secrete immunosuppressive cytokines, and actively contribute to the formation of the drug resistant niche, finally enabling the regrowth of the tumor cells." (PMID 39747003, 2025).
tumor (continued). "Finally, the subcutaneous tumour experiment results also showed that silencing HEY1 inhibits the growth of OS through the CD44/EGFR/FAK pathway." (PMID 40531089, 2025). "To investigate whether ginsenoside Rg3 could exert potentiating anti-cancer effects on EGFR-TKI agents by down-regulating the copy number and expression of EGFR protein, we performed mouse tumor-loading experiments." (PMID 40732366, 2025). "Gel@Cmab/PCZ promoted NK cell infiltration into tumor tissues, which may be attributed to the increased accumulation of anti‐EGFR antibodies on the tumor surface." (PMID 39560161, 2025). "Similarly, erlotinib induced higher levels of cetuximab binding to EGFR on NSCLC tumor cells, which translated to enhanced cytotoxicity and a stronger in vivo anti-cancer effect." (PMID 40452841, 2025). "The treatment with PYCR1-IN-1 markedly reduced the cell proliferation and the tumor spheroid size induced by the EGFR or TLR agonist in H1975 and HCC827 cells compared with cells treated with EGF or TLR agonists alone (vehicle versus PYCR1-IN-1 in H1975, vehicle versus PYCR1-IN-1 in HCC827)." (PMID 41254241, 2025). "Thus, EGFR amplifications not only promote the invasiveness of GBM tumor cells but also contribute to their resistance to EGFR-targeted therapies." (PMID 39859381, 2025). "Given the intricate involvement of EGFR in multiple signaling pathways, its pivotal role in tumor growth, survival, and resistance mechanisms, and its frequent amplification and mutation in GBM, EGFR stands as a crucial target for future research and therapeutic interventions." (PMID 40332008, 2025). "We next explored the role of mTOR and EGFR pathway activation in EY-mediated tumor initiation." (PMID 39779672, 2025). "Previous studies found that pre-existing T790M may exist in many TKI-naive NSCLCs, and may become the dominant tumor population as a result of drug pressure in EGFR TKIs resistant NSCLC patients." (PMID 40242250, 2025). "Anti-EGFR therapies, such as cetuximab, work by binding to the EGFR on cancer cells, blocking its activation, and inhibiting downstream signaling pathways that promote tumor growth." (PMID 39851804, 2025). "Tumor cells may develop drug resistance through various mechanisms, including overexpressing certain proteins (e.g., epidermal growth factor receptor/EGFR, insulin-like growth factor-1 receptor/IGF-1R, c-KIT), which can lead to inhibition of drug efficacy." (PMID 40584293, 2025). "Although she was not eligible for targeted therapy due to the absence of actionable mutations such as ALK or EGFR, her tumor’s PD-L1 expression of 30% supported the use of immune checkpoint inhibitors." (PMID 41018467, 2025). "Furthermore, the relationship between EGFR.Sig and ITH, which is a stem-related trait associated with tumor immunosuppression, was analysed." (PMID 40574864, 2025). "Therefore, FA reduction in the presence of EGFR amplification indicates a mechanism of accelerated tumor infiltration." (PMID 40941753, 2025). "Furthermore, treatment with EGFR-TKI erlotinib significantly decreased tumor size in the shMEOX2 group, indicating a potential interaction between MEOX2 and EGFR signaling." (PMID 39971779, 2025). "EREG, in turn, stimulates tumor-promoting signals, leading to EGFR-TKI resistance in NSCLC cells." (PMID 40003951, 2025).
tumor (continued). "Additionally, the EGFR signaling pathway itself can reciprocally regulate global epigenetic modification patterns, affecting changes in the tumor cell phenotype." (PMID 40486879, 2025). "By applying mass spectrometry or affinity-based assays to tumor tissue, plasma, or enriched exosomes, clinicians can identify overexpressed receptor tyrosine kinases (e.g., EGFR, HER2) or activated signaling nodes (e.g., phosphorylated AKT, ERK) that constitute actionable targets." (PMID 41301080, 2025). "Furthermore, the lead candidate FH-EB02 demonstrated optimal efficacy-selectivity balance and robust tumor suppression in EGFR/B7H3-coexpressing CDX and PDX models." (PMID 41291854, 2025). "CAFs are well-established mediators of tumor progression and resistance to anti-EGFR therapies." (PMID 40362183, 2025). "While resistance mechanisms such as elevated KRAS or EGFR activity can lead to emergent drug resistance in some tumours, the primary mode(s) of resistance for many CRC tumours remain unclear." (PMID 41188521, 2025). "While in other tumor entities HDACi-mediated alterations of EGFR expression appear to be cell context-dependent and may also depend on the HDACi used, findings of EGFR downregulation overall predominate." (PMID 39864337, 2025). "In addition, EphA2 overexpression has been associated with resistance to multiple EGFR-targeted TKIs in other malignancies, where EphA2 blockade with ALW-II-41-27 reversed acquired resistance and re-sensitized tumor cells to erlotinib and afatinib." (PMID 41440001, 2025). "All patients had high PD-L1 expression (Tumor Proportion Score ≥50%), and tested negative for activating mutations, such as EGFR mutations or ALK rearrangements." (PMID 40959419, 2025). "Human EGFR expressed on various tumor types was selected as the target." (PMID 41516067, 2025). "EGFR activation in macrophages affects tumor treatment through the following mechanisms." (PMID 40859900, 2025). "Moreover, pre-clinical studies suggested that MK2206, in combination with other targeted therapies like mTOR inhibitors or Epidermal Growth Factor Receptor (EGFR) inhibitors, can enhance anti-tumor activity and overcome resistance to single-agent treatments." (PMID 40943298, 2025). "In these instances, constitutively active forms of EGFR promote tumor growth 9,10." (PMID 40535815, 2025). "DP‐V‐4 showed superior activity compared with that of single‐agent degraders in preclinical models, where it displayed over 70% tumor growth inhibition, particularly in osimertinib‐resistant EGFR‐mutant NSCLC, demonstrating the potential of this strategy to deplete redundant oncogenic pathways." (PMID 41362117, 2025). "However, due to complex mechanisms such as tumor heterogeneity, compensatory activation of signaling pathways, and immune escape, almost all patients treated with EGFR-TKIs will eventually develop acquired resistance, leading to disease progression." (PMID 40959071, 2025). "Finally, to further investigate the therapeutic responses of EGFR-mutant cancers, we utilized a novel tumor-on-a-chip (TOC) system." (PMID 39747003, 2025). "Early tumor shrinkage positivity was associated with improved overall survival, PFS, and postprogression survival in anti-EGFR and bevacizumab-based therapies, with a trend toward better outcomes in the anti-EGFR group." (PMID 40280867, 2025). "Therefore, targeting CBL-c represents a promising strategy to suppress tumor growth and improve the therapeutic response of EGFR-mutant NSCLC to tyrosine kinase inhibitor treatment." (PMID 40165954, 2025). "For evaluating possible impacts of the secretome of the hAMSCs on tumor growth plus progress via EGFR/c-Src/IRSp53/p-AKT/p-Stat3/cyclin D1 signaling pathway, first coculturing of HT-29 colon cancerous cells /hAMSCs was fulfilled for 72 h afterward, they underwent MTT assay." (PMID 41200137, 2025).
tumor (continued). "This phenomenon may be attributed to the role of intracellular EGFR signaling in directly or indirectly upregulating PD-L1 expression in tumor cells, thereby facilitating T-cell apoptosis and promoting immune evasion." (PMID 39833943, 2025). "Finally, co-delivery of two mRNA-encoded bsAbs (EGFR x CD3 and PD-L1 × 4-1BB) demonstrated synergistic tumor inhibition in a colorectal cancer model, highlighting the potential of multiplexed mRNA nanotherapies." (PMID 41250091, 2025). "BsAbs targeting HER2 and EGFR, key oncogenic drivers in multiple tumor types, may benefit from the lessons learned in antibody‐drug conjugates (ADCs) design to improve target selectivity and optimize therapeutic windows." (PMID 41388342, 2025). "Sequencing of the tumor revealed the lack of EGFR, KRAS or ALK mutations, rendering the patient ineligible for targeted therapy options." (PMID 41146188, 2025). "In cancer, this high-affinity interaction may sustain EGFR activation, promoting aggressive tumor behavior and potentially reducing the efficacy of EGFR-targeted therapies." (PMID 40004194, 2025). "PD‐L1, PD‐L2, and EGFR expression changed in 30%–40% of tumor pairs." (PMID 40156197, 2025). "Protein arginine methyltransferase 1(PRMT1) enhances CRC proliferation by asymmetrically dimethylating the non-POU domain-containing octamer-binding protein (NONO) at R251, facilitating epidermal growth factor receptor (EGFR) signaling activation and tumor progression." (PMID 40951358, 2025). "Similarly, in a breast xenograft tumor model, it was found that PD-L1 glycosylation mediated by the EGFR/B3GNT3 pathway suppresses the autophagic degradation of PD-L1, and in turn, promotes tumor immune escape." (PMID 40422248, 2025). "The out-of-range low IC Ct values of these specimens, as reported by the cobas test, suggest that these tumor cells might have unusually high EGFR amplification values, which exceeds the normal range of most NSCLC specimens." (PMID 40310364, 2025). "Accordingly, the ESMO recommendation for patients with EGFR-mutated NSCLC who progress on TKI therapy is to assess actionable mechanisms of resistance on tissue rebiopsy when possible or on circulating tumor DNA (ctDNA) when no tissue is available." (PMID 40243603, 2025). "Therefore, we further screened the potentially available drugs for tumor immune regulation based on Hub-EGFR.Sig." (PMID 40574864, 2025). "Theoretically, the presence of EGFR mutations in NSCLC could influence the microscopic characteristics and growth patterns of tumor cells, and these features can be captured through pathomics approaches." (PMID 40969259, 2025). "Furthermore, samples with 5–10% tumor content, including those from EGFR_12, EGFR_2, KRAS_18, and KRAS_26, clustered together with other samples harboring the same mutation." (PMID 40621945, 2025). "Furthermore, irrespective of the number of baseline targeted lesions or total tumor diameter, the median depth of response was 0.5 to 0.7 in the anti-EGFR antibody group, 0.4 to 0.5 in the bevacizumab group, and 0.4 to 0.5 in the chemotherapy-alone group." (PMID 40280867, 2025). "In a recent study, the design of a nano-cage on tetrahedral DNA encapsulating therapeutic siRNA demonstrated effective endosomal escape and down-regulation of epidermal growth factor receptor (EGFR) expression in A549 tumor cells, thereby significantly inhibiting tumor growth." (PMID 40948789, 2025). "One possible explanation involves the tumor microenvironment (TME) in NSCLC with certain genetic alterations, such as EGFR or ALK, which have been associated with reduced immunogenicity and often exhibit lower tumor mutational burden (TMB) and decreased neoantigen load." (PMID 40961974, 2025).
tumor (continued). "The amplification of chromosomal regions containing the genes EGFR, MET, KIT, and PDGFRA is associated with the receptor tyrosine kinase (RTK) and growth-factor receptors, often driving proliferative and angiogenic signalling in tumours." (PMID 41573648, 2025). "Furthermore, in clinical trial of ESCC, several studies have shown that EGFR inhibitors (erlotinib, icotinib, larotinib) display anti-tumor effects, especially in patients with EGFR overexpression." (PMID 40693409, 2025). "EGFR is expressed not only in tumor cells but also in CD4+ T lymphocytes." (PMID 40502915, 2025). "The comprehensive view of PET/MR may improve predictions of tumor characteristics and molecular expressions like EGFR and HPV status." (PMID 40875092, 2025). "Amplifications and mutations of the EGFR gene, particularly within the extracellular domain, result in constitutive activation of downstream signaling pathways such as PI3K/AKT and MAPK, thereby promoting tumor cell proliferation, invasion, and angiogenesis." (PMID 40942013, 2025). "Current studies have demonstrated that TUSC2 might play a tumor-suppressing role through inducing apoptosis, arresting the G1 cell cycle, and inhibiting proliferation-related kinases, e.g., EGFR, mTOR, and AKT." (PMID 40243558, 2025). "As we will discuss later, EGFR-mutant NSCLC is notoriously resistant to immunotherapy, which may be due in part to its uniquely immunosuppressive TME and low tumor mutational burden." (PMID 40507214, 2025). "EGFR plays a critical role in tumor cell growth, survival, and metastasis." (PMID 40621224, 2025). "Although various mutations are associated with upregulation of PD-L1 expression in tumor cells, the mechanisms of decreased efficacy of ICI on EGFR-and ALK-driven NSCLC remains unclear." (PMID 40809430, 2025). "Challenges remain: low-level EGFR expression in normal tissues raises on-target/off-tumor toxicity concerns; brain accumulation after intravenous dosing is constrained by the BBB; and sustained IL-15 signaling may promote NK-cell exhaustion." (PMID 41209565, 2025). "The co-expression of EGFR and HER2 has been linked to more aggressive tumor behavior." (PMID 40642068, 2025). "CAV1 functions as a scaffolding molecule for several signaling molecules, including epidermal growth factor receptor (EGFR), and its overexpression and tumor‐promoting activity are associated with metastasis and poor prognosis in bladder, lung, cervical, and other cancers." (PMID 40419438, 2025). "Evidence suggests afatinib may be the most effective EGFR inhibitor due to its concurrent breakdown of brachyury, enhancing its anti-tumor effect." (PMID 41404256, 2025). "MOR has been associated with several protumorigenic properties: the co‐activation of EGFR, the promoting of epithelial mesenchymal transition (EMT) which gives tumor cells their migrative and invasive properties, and the activation of various other tumor‐promoting pathways outside of EGFR." (PMID 40650440, 2025). "Thus, amivantamab, designed for dual inhibition of EGFR and cMET, was developed and demonstrated promising tumor inhibition activities in preclinical and clinical studies." (PMID 40452841, 2025). "The H3K27ac modification may activate NAT10-related signaling pathways, promote fatty acid oxidation, and stimulate tumor energy metabolism, ultimately exacerbating tumor cell resistance to EGFR-TKIs." (PMID 41310903, 2025). "In ESCC, preclinical studies report tumor-suppressive functions via targeting oncogenic pathways (e.g., cell division cycle 42 (Cdc42)-mediated invasion (Sharma, Saini & Sharma, 2017), epidermal growth factor receptor/phosphatidylinositol 3-kinase/ak strain transforming (EGFR/PI3K-AKT) signaling)." (PMID 41215804, 2025). "In tumour cells of epithelial origin, interactions between EGFR and EpCAM have been demonstrated." (PMID 39939830, 2025). "Furthermore, high THOC5 was also indicated to activate several tumor signaling pathways, such as EGFR, Hypoxia and MAPK pathways." (PMID 40901498, 2025).